CCL2 (C-C motif chemokine ligand 2)
Diseases named in the same sentence as CCL2 in open-access papers (continued):
Sharing a sentence is not in itself a finding about the gene and the disease.
infection (continued). "Primary histological and immunological studies using this model reveal massive infiltration by immune cells, mainly monocytes and neutrophils, and an increase in expression of CCL2 mRNA and protein in the liver at early time points post-intrahepatic infection with axenically cultured trophozoites." (PMID 33829283, 2021). "Confirming the observations made above, infection with all three L. major induces (cluster 1) neutrophil recruitment, myeloid activation, and production of cytokines/chemokines (e.g. Trem1, Trem3, C5ar1, Ltf, Ptgs2, Ccl2, Ccl12, Ccl17, etc.)." (PMID 34972189, 2021). "Notably, the majority chemokine ligand, which induced cells of the immune system to enter the site of infection, CCL-2, CD80 and CD68 of TAMs, IRF5 and NOS2 of M1, CD163 and MS4A4A of M2 were strongly related to JAK1 expression in LUAD (all P value < 0.0001)." (PMID 34587898, 2021). "It has been reported that the infection with SARS-CoV-2 can cause a cytokine storm in patients with symptoms severe or critical, consisting of an increase of IL-1β, IL-4, IL-6, IL-10, IL-17, TNF-α, G-CSF, GM-CSF, IFN-γ, CCL2, CXCL8, and CXCL10." (PMID 33917837, 2021). "At 3 day post-infection, higher mRNA levels of C-C motif chemokine ligand 2 (CCL2), C-C motif chemokine ligand 3 (CCL3) and C-X-C motif chemokine ligand 10 (CXCL10) were found in the liver of mice infected with the WT strain as compared to mice infected with the ΔspvB strain." (PMID 33475464, 2021). "Indeed, CCL2 (MCP-1) is a member of the small inducible gene family that plays a role in the recruitment of monocytes to sites of injury and infection, but also to AT under conditions of inflammation or adipocyte apoptosis." (PMID 33540898, 2021). "UDP-mediated activation of P2Y6 receptor promotes the recruitment of inflammatory cells to sites of inflammation or infection by inducing the production of various chemokines including CCL2 (monocyte chemotactic protein 1, MCP-1), CXCL8 (IL-8) and CCL20 (macrophage inflammatory protein-3α, MIP-3α)." (PMID 34064383, 2021). "In this study, we found that the chemoattractive molecules CXCL10, CCL5, and CCL2 were potently released by the apical compartment upon ZIKV hBLEC infection, suggesting that circulating leukocytes could be attracted to the infected BBB." (PMID 32753493, 2020). "Similarly, in the brain, CCL2 was upregulated in both males and females at 24 h but only in males at 5 d after the infection." (PMID 32373108, 2020). "Decreased levels of circulating CCL2 could therefore contribute to reduce the local immune response to infection in FXS patients." (PMID 32295518, 2020). "Similarly, the infection elevated plasma CCL2 levels, and simvastatin worked by reducing this chemokine only in the group of infected animals fed a high-fat diet." (PMID 32596277, 2020). "The recruitment of these permissive monocytes and their function at the infection site can be inhibited by morpholinos against either ccr2 or its ligand, ccl2, but the role of the Ccl2–Ccr2 signaling axis in other inflammatory responses is unknown." (PMID 31932292, 2020). "Il1β, Tnf, Il6, Ccl2, Ccl5, and Cxcl10 mRNAs were all increased in the CNS after infection." (PMID 32047134, 2020). "The level of CCL2 mRNA in the lungs of klotho WT mice gradually increased after infection, whereas those of klotho KO mice significantly increased at 1 day post-infection and subsequently decreased at 3 days post-infection." (PMID 33329595, 2020). "During both phases of infection, Ccl2 induction in diabetic mice was lower compared to WT mice." (PMID 33613280, 2020). "Lung Ccl2 expression coincided with the peak of inflammatory monocyte/macrophage accumulation in WT mice and was significantly higher during the initial phase of infection." (PMID 33613280, 2020). "Furthermore, IP-10 and CCL2 production was induced by productive infection of iCell-MGs by HIV-1 and inhibited upon treatment by EFV, Ral, or verdinexor." (PMID 33298546, 2020).
infection (continued). "Following infection of the CNS, microglia express markers characteristic of M1 activation including increased expression of Iba-1, as well as chemokines such as C-C motif cytokine 2 (CCL2), CCL3, CCL5, and CCL7." (PMID 32872152, 2020). "Infection with Mtb in the post-drug relapse phase, however, was associated with pulmonary activation of several pro-inflammatory cytokines and chemokines that have established roles in enhancing HIV replication including IL-1β, IL-6, TNF-α, and CCL-2." (PMID 32373548, 2020). "Among affected virus-related-infection proteins, we also identified CCL2." (PMID 33233425, 2020). "In addition, also the extent of gene expression variation was increased at this stage of infection (i.e., up to >8-fold change seen for the inflammatory chemokines CCL2 and CCL3) as compared to the acute phase, where a maximum of 3-fold variation was observed." (PMID 31018522, 2019). "The levels of CCL2 were constantly high in the middle ear fluid before and after NTHi infection." (PMID 31548315, 2019). "The chemokine CCL2 (= MCP-1) attracts CCR2+ monocytes to sites of infection." (PMID 30800124, 2019). "Pro-inflammatory cytokines (IL-6, TNF-α, IL-12, IFN-γ, and the chemokine CCL2/MCP-1) were up-regulated in plasma of morphine-treated mice collected 8 h after infection, which was interpreted to be the result of the increased systemic bacterial burdens with the pathogen in animals given morphine." (PMID 31921165, 2019). "Additionally, in a study in vitro using a WT hRSV A2 strain (6340WT) and a recombinant strain that lacks the G-protein gene (6340ΔG), infection of NHBEs cells induced the secretion of CCL2, CCL5, and CXCL8 by both viruses." (PMID 30936869, 2019). "Interestingly, MCP-1/CCL2 levels were enhanced after infection with L. amazonensis, but melatonin treatment reduced this chemokine production in infected macrophages." (PMID 30949455, 2019). "Furthermore, MCP-1, known as CCL2, acts to recruit monocytes, memory T cells, and dendritic cells to the lesion of inflammation produced by either tissue injury or infection." (PMID 31130697, 2019). "Amongst cytokines, the genes for Cxcl9, Cxcl10, Cxcl13, Il-1β, Il-6, Tnf, Tnfsf10, IFN-γ, Ccl2, Ccl4, Ccl7, Ccl17, and Mif were highly up-regulated (ranging from 2- to 405-fold, p ≤ 0.05), whereas Cxcl12 and Cxcl14 were down-regulated during in vivo infection." (PMID 30857242, 2019). "CCL2 may thus partially protect from infection, but it may accelerate disease progression and increase the risk of HAND once infection is established, through its pro-inflammatory properties and ability to stimulate HIV replication." (PMID 31377844, 2019). "Growth factors and chemokines that support myeloid cell influx and expansion after infection, including M-CSF, G-CSF, MCP-1 (CCL2), MIP-1α (CCL3), MIP-1β (CCL4), KC (CXCL1) and MIP-2 (CXCL2), are also highly abundant in S. aureus infected femurs relative to mock infected femurs." (PMID 30978245, 2019). "The transmigration of HIV-infected monocytes into the CNS, mainly mediated by CCL2, transports the virus into the CNS, resulting in infection of macrophages and microglia thus contributing to the establishment and maintenance of the CNS viral reservoir and to HAND." (PMID 31377844, 2019). "However, statically significant difference in leptospires phagocytosis by RAW cells CCL2-treated was observed between 1 h and 2 h after infection." (PMID 30616505, 2019). "However, the levels of IL-6, MCP-1 (CCL2), IL-10, and Arg-1 mRNA were found to be downregulated at 6 weeks post-infection." (PMID 30589840, 2018). "Moreover, quantitative RT-PCR and ELISA performed in the LMMP of WT mice at 1–3 weeks post IG infection revealed increased mRNA and protein levels of CCL2, a chemoattractant factor involved in macrophage-driven tissue damage." (PMID 30254622, 2018).
infection (continued). "In infection models, there are also two distinct subpopulations of neutrophils: pro-inflammatory neutrophils (N1: IL-12 and macrophage inflammatory proteins producing) and anti-inflammatory neutrophils (N2: IL-10 and CCL2 producing)." (PMID 29776443, 2018). "In fact, TNF-α acts synergistically with IFN-γ to stimulate the production of nitric oxide (NO) by macrophages and influences the expression of chemokines, such as CCL5, CCL9, CXCL10, and CCL2, which induce migration to and maintenance of immune cells in the infection site." (PMID 28659665, 2017). "CCL2 was induced in a PGL-dependent fashion at 60 min post-infection (Donor 1)." (PMID 28844797, 2017). "Importantly, treatment with aprepitant significantly attenuated increases in CCL2 protein levels at 2 weeks following infection in this experimental series." (PMID 28202084, 2017). "Importantly, daily treatment with aprepitant significantly attenuated infection-associated increases in CXCL13 and CCL2 mRNA expression." (PMID 28202084, 2017). "Whether EHV-1 infection is activating the attraction of CD172a+ monocytic cells to the infection sites and whether CCL2 and CCL5 are driving forces during this process are largely unknown." (PMID 28241864, 2017). "Similarly, type I IFN was shown to modulate the recruitment of myeloid cells by influencing CCL2 signaling during infection with the intracellular pathogens Listeria monocytogenes and Mycobacterium tuberculosis." (PMID 28894449, 2017). "CCL2 and RNase L were inhibited by JXwn06 infection compared with BHK-21 cells." (PMID 27182980, 2016). "In support of studies reporting increased susceptibility to infection with AUD, we report down-regulation of a number of genes important for host defense such as cytokines (IL1R1 and TNFSF11), chemokines (CCL2), and receptors (TGFBR1 and TLR8)." (PMID 27427759, 2016). "For instance, mice lacking MyD88, the common adaptor protein for many Plasmodium-stimulated TLRs, exhibited diminished blood inflammatory cytokines (IL-6, IL-12, IFNα, IFNγ, TNF, CCL2) in several of the murine models, leading to improved resistance to these infections." (PMID 27792766, 2016). "In aggregate, the reduced levels of CCL2 in A20AEC-KO mice could explain their increased tolerance to the infection." (PMID 26815999, 2016). "Interestingly, while JMJD3 was found to negatively regulate few of the mycobacteria-responsive M1 markers of macrophages viz., Il12, Il1b and Cxcl2, the expression of M2 markers like Arg1, Mrc1, Il10, Tgfb, Ccl17 and Ccl2 on infection were JMJD3-dependent." (PMID 27532872, 2016). "Examination of chemokine expression at memory showed that infection resulted in sustained upregulation of transcripts encoding for a variety of different chemokines, including CCL1, CCL2, CCL5, CCL8, CXCL9 and CXCL10 compared with control flank skin from the same animals." (PMID 27160938, 2016). "The minimal effect of anti-IL-17A treatment on Ccl2 and rather a slightly decreased gene expression of Zc3h12a in lung tissue at day 28, suggest a dispensable role for IL-17A at this stage of the infection." (PMID 27853279, 2016). "Therefore, MDM were treated with anti-CCL2 Ab 20 h before or at the time of infection, and viral DNA accumulation and the proportion of p24 Gag+ cells were measured 7 and 14 days post-infection, respectively." (PMID 25608886, 2015). "In spite of an occasional effect of control Ab on the level of HIV-1 DNA, the presence of anti-CCL2 Ab significantly reduced the amount of viral DNA copies accumulated 7 days post-infection with respect to control Ab treatment [0.26 ± 0.09 (SE) fold vs. control Ab; p < 0.001; n = 13]." (PMID 25608886, 2015). "Consistently, infection of MDM with HIV-1 in the presence of anti-CCL2 Ab resulted in a potent inhibition of p24 Gag Ag release with respect to control cells, in the intracellular accumulation of this viral antigen and in remarkable changes in cell morphology and size." (PMID 25608886, 2015).
infection (continued). "The chemokine MCP-1 (CCL2), which contributes to monocyte recruitment to sites of infection, was significantly higher at all time points in the propofol-treated groups, as were the eosinophil chemoattractant eotaxin and the neutrophil chemoattractant KC (CXCL1)." (PMID 26381144, 2015). "The expression of CCL2 also improved significantly during the early infection phase." (PMID 26070790, 2015). "Here, cytokine and chemokine production during HSV-2 infection showed size-related differences for each nanoparticle type - presence of 13 nm AgNPs at the time of infection led to production of CCL2, IFN-γ and IL-10, while 33 nm AgNPs induced CCL2, TNF-α and IL-10." (PMID 25117537, 2014). "Indeed, CCL2 is detected in the plasma of WNV-infected blood donors during the acute phase of infection, and numerous studies have also shown strong induction of CCL2 in vitro." (PMID 25324719, 2014). "TgCyp18 may also play a role with CCL5 in the migration of macrophages to the site of infection, and with CCL2 and CXCL10 in the transport of T. gondii-infected cells to the liver." (PMID 24661782, 2014). "Hence, in mice deficient for CCR2, a receptor for CCL2 and CCL8, the number and size of granulomas, as well as monocyte recruitment at site of infection, are decreased." (PMID 25566510, 2014). "The lower accumulation of inflammatory monocytes in Mif−/− mice at this stage of infection could result from the reduced expression of Ccl2 and/or increased production of IL-10." (PMID 25255103, 2014). "Infection with both low and high virulence isolates resulted in down-regulation of mRNA levels for chemokines CCL2, CCL3L, CXCL2 and chemokine receptors CCR1, CCR5, CXCR3, CXCR4 and up-regulation in expression of mRNAs for CCL4, CXCL10 and chemokine receptor CCR7." (PMID 23265239, 2013). "In wild type hosts the infection-induced mobilization of myeloid progenitors via CCL2/CCR2 resulted in the presence of “CD27+ CMPs” and “GMPs” in the spleen, inversely corresponding to their loss from BM following infection." (PMID 23762028, 2013). "Levels of CCL2 protein secreted may be influenced by factors other than the mRNA level at 16 h post-infection." (PMID 23265239, 2013). "By contrast, at 7 days post infection, the levels of CCL2, CCL3, CXCL2, IFN-γ and the anti-inflammatory cytokine IL-10 were significantly lower in influenza A virus-infected Nox1−/y lung compared to WT control, whereas IL-β, IL-6, TNF-α, and GM-CSF were similar between the two strains of mice." (PMID 23577160, 2013). "Secretion of C-C chemokine ligand 2 (CCL2) by injured or inflamed tissue cells induces migration of these Ly6ChiCCR2+ monocytes from the bone marrow to the site of infection, where they are involved in the immune defense responses against pathogenic microorganisms." (PMID 23300453, 2013). "Indeed, when similar infectious doses are applied, although infection with virulent Kp52.145 is lethal, the cytokines IL-1β, IL-6, and IL-17 and the chemokines CCL2, CCL3 and CCL4 are produced in similar manner." (PMID 23554169, 2013). "In addition, treatment with rMCP-1/CCL2 increased bacterial clearance and protected mice after infection with Pseudomonas aeruginosa or Salmonella Typhimurium." (PMID 24069320, 2013). "However, at later stages of infection, IFNs-I become central mediators of CCL2/CCL7 production and monocyte egression." (PMID 22911155, 2012). "It has been shown that CCL5 and CCL2 expression, detectable following infection with a HCMV strain Towne US28 deletion mutant, could induce monocyte chemotaxis that was inhibited by infection with the parental strain expressing US28." (PMID 23202490, 2012). "Infection with L. tropica led to increased serum levels of chemokines CCL2, CCL3 and CCL5." (PMID 22679519, 2012). "In addition, PR/8 infection up-regulated mRNA expression of many chemokine genes including CC chemokines CCL2–5, and CCL20, as well as CXC chemokines CXCL9–11." (PMID 22396727, 2012).
infection (continued). "Similarly, there was a significant increase in CCL2 by more than 7-fold after 3 d of infection and more than 20-fold increase on 5 and 7 d.p.i. respectively." (PMID 22393394, 2012). "However, these cells clearly were responding to the infection, as Ccl2, Ccl3, and Il1β were upregulated in expression compared to cells from non-infected mice." (PMID 23248776, 2012). "In addition to early induction of CXC chemokines, we also show that induction of genes encoding C-C chemokines namely CCL-2 (MCP-1), CCL8 (MCP-2), CCL12 (MCP-5) and CCL22 (MDC) occurs on D12 and progressively increases between D15 and D21 post infection." (PMID 21249199, 2011). "In the case of HIV infection, CCL2 facilitates the recruitment of uninfected cells to areas of infection within the brain where infected monocytes may spread the virus." (PMID 21760952, 2011). "CCL2 is essential for the recruitment of mononuclear cells and subsequent activation of T lymphocytes, mononuclear and polymorphonuclear cells at the site of infection." (PMID 21556333, 2011). "In TB endemic regions concomitant infections with helminths can also skew the immune response towards Th2 and may enhance CCL2 responses which forms part of the Th2 loop." (PMID 21991356, 2011). "Plasma CCL2 levels increased at 9 days post infection and then moderately decreased in all animals, except one slow progressor whose CCL2 concentration returned to pre-infection levels (rapid progressors = solid lines, slow progressors = dotted lines)." (PMID 20419144, 2010). "In our model, some chemokines reported to be part of the "1st and 2nd waves" of chemokine expression by DC cells, specifically Xcl1, Cxcl9, Cxcl16, Ccl1, Ccl2, Ccl3, Ccl4, Ccl5, Ccl7 and Ccl8 are expressed at increased levels in lung i.n. samples at 3 weeks post-infection." (PMID 20942964, 2010). "In addition, CCL2 protein levels in the blood and gene expression of Ccl2 in total liver extracts of infected mice was increased by anti-IL-10R treatment during infection." (PMID 20714353, 2010). "Here we demonstrate the temporal correlation between a significantly stronger and transient expression of macrophage chemoattractants (CCL5, CCL2 and opn) with a peak after 8h post infection and an ensuing significantly more pronounced macrophage infiltration 3 days after infection." (PMID 20442861, 2010). "Expression of the chemokines genes (Ccl-2, >200-fold; csf2, >10-fold and Ccxl-10, ∼30-fold) and surface receptor molecules (FasL, >2.5 fold and IL-2R, 4-fold) were upregulated at the initial phase of infection, but decreased at later time points." (PMID 20062542, 2010). "In addition, the induction of the cytokines IL6, IL10, and the chemokine CCL2 occurred during acute infection." (PMID 20019816, 2009). "CCL2 is responsible for the recruitment of leucocytes to the site of infection and therefore raised CCL2 may be characteristic of granuloma formation and the influx of monocyte driven responses." (PMID 20041183, 2009). "Infection with HTLV-1A/CoI-L resulted in low overall frequency of monocytes, DCs, and neutrophils producing IL-10, with elevated frequencies of those producing TNF-α in both compartments, linked to high expression of IL-6, CCL2, and IL-33 in blood and of MMP1, IL-1β, CCL3, and CCL19 in the lung." (PMID 41006234, 2025). "However, indicating a broader inflammatory response in the whole brain, transcripts encoding pro-inflammatory cytokines, such as interleukin-1α (IL-1α), interleukin-6 (IL-6), interleukin-8 (IL8/CXCL1), and especially MCP1/CCL2, exhibited significant upregulation at 2- or 4-days post-infection." (PMID 40365287, 2025). "Similarly, activated microglia can also release chemokines such as CCL2, CXCL10, and CX3CL1, that can mediate the recruitment of additional inflammatory cells, including peripheral immune cells, to the site of infection, thereby amplifying the inflammatory response and associated neurotoxicity." (PMID 41221080, 2025).